SMYD4 (SET and MYND domain containing 4)
Description:
Protein-lysine N-methyltransferase. Monomethylates PRMT5, modulating its transcriptional activity. May also act as a histone methyltransferase (By similarity). Plays a critical role in cardiac development. Acts as a key epigenetic regulator of gene expression during cardiac development via its dual activities as a methyltransferase and negative regulator of HDAC1 (By similarity).
Synonyms: KIAA1936; ZMYND21
Tractability: PROTAC: ubiquitination databases record sites on it.
Gene: Protein-coding gene on chromosome 17 (1,779,485 to 1,830,634, reverse strand). Ensembl gene ENSG00000186532.
Subcellular location: Nucleus; Cytoplasm
Subcellular location (Human Protein Atlas): Golgi apparatus; Vesicles; Cytosol; Nucleoplasm
Gene Ontology:
Molecular function: protein binding; protein-lysine N-methyltransferase activity; histone deacetylase binding
Biological process: heart development
Cellular component: cytoplasm; nucleus
Genetic constraint (gnomAD): Loss-of-function variants: 65 observed, 69.78 expected, observed/expected ratio (o/e) 0.93, 90% interval 0.76 to 1.14. The upper end of that interval is the gene's LOEUF score, 1.14, which puts it in group 5 of 6, group 1 being the genes least tolerant of losing a copy. Missense variants: 900 observed, 946.8 expected, observed/expected ratio (o/e) 0.95, 90% interval 0.9 to 1. Synonymous variants: 377 observed, 371.07 expected, observed/expected ratio (o/e) 1.02, 90% interval 0.93 to 1.11.
Homologues: Orthologues: chimpanzee SMYD4 (99% identical), macaque SMYD4 (91% identical), guinea pig SMYD4 (76% identical), rabbit SMYD4 (75% identical), pig SMYD4 (75% identical), rat Smyd4 (73% identical), mouse Smyd4 (72% identical), dog SMYD4 (71% identical), tropical clawed frog smyd4 (39% identical), zebrafish smyd4 (33% identical), Drosophila melanogaster dao (21% identical), Drosophila melanogaster Smyd4-1 (20% identical), and 7 more. Paralogues in human: SMYD2 (13% identical), SMYD1 (13% identical), SMYD3 (13% identical), ZMYND15 (11% identical), SMYD5 (11% identical).
Diseases named in the same sentence as SMYD4 in open-access papers:
SMYD4 is named in the same sentence as 21 diseases in open-access papers, as found by Europe PMC text mining. Sharing a sentence is not in itself a finding about the gene and the disease. The quoted sentences say what the papers report.
breast carcinoma (15 papers, 2013 to 2026). "For example, in the early stages of breast cancer of a various molecular subtypes (luminal, triple negative), miR-1307-3p significantly targets the mRNA encoding the SMYD4 protein identified as a tumor suppressor in breast cancer." (PMID 35922756, 2022). "SMYD4 has been related to breast cancer, and work from our group has revealed that mutations in SMYD4 could be related to an inherited rare neuropathy (unpublished data)." (PMID 26230726, 2015). "The few existing studies have suggested that SMYD4 acts as a tumor suppressor in breast cancer by locally inhibiting platelet growth factor receptor, while miR-1307-3p can promote tumor cell proliferation by targeting SMYD4 transcripts." (PMID 36816359, 2023). "The tumor suppressor function of SMYD4 has been documented in relation to breast cancer development." (PMID 38036730, 2023). "It has been proved that miR-1307-3p is upregulated in breast cancer tissues and significantly contributes to breast cancer development by targeting SMYD4." (PMID 35864511, 2022). "In some specimens of human breast cancer tested reverse transcription-PCR results revealed that SMYD4 expression was totally silenced." (PMID 36520265, 2022). "The finding revealed that SMYD4 exerts tumor suppression in breast cancer through the partial inhibitory effect of PDGFa." (PMID 36520265, 2022). "A study in breast cancer suggests that re-expression of SMYD4 suppresses growth of tumor cells and inhibits formation of xenografted tumor in nude mice." (PMID 36520265, 2022). "SMYD4 acts as a tumor suppressor gene in breast cancer cells and directly inhibits the gene expression of platelet-derived growth factor receptor A polypeptide (Pdgfr-A), thereby inhibiting tumor growth." (PMID 33292243, 2020). "In breast cancer, SMYD4 has been suggested to act as a tumor suppressor gene." (PMID 39482529, 2024). "SMYD4 has been identified as a tumor suppressor gene in breast cancer, and SMYD5 may be involved in cancer and stem cell maintenance." (PMID 36816359, 2023). "An early study pointed to the role of SMYD4 as a tumor suppressor in breast cancer." (PMID 36520265, 2022). "SMYD4 was also reported to be a tumor suppressor of breast cancer." (PMID 31548876, 2019). "SMYD4 was identified as a potential tumor suppressor gene involved in breast cancer development." (PMID 29487338, 2018). "Finally, the SMYD4 gene was recently identified as a potential tumour suppressor gene in breast cancer." (PMID 23359294, 2013). "While SMYD4 has been less studied in carcinogenesis compared to other members of the SMYD family, it has been identified as a potential tumor suppressor due to its observed downregulation in breast cancer." (PMID 38892284, 2024). "In BRCA, there was a small negative correlation between SMYD4 and SMYD3, which is expected since SMYD3 upregulation is already known to be associated with breast cancer proliferation." (PMID 38892284, 2024).
hepatocellular carcinoma (2 papers, 2024). A malignant tumor that arises from hepatocytes. "A recent study also reports that SMYD4 is upregulated in hepatocellular carcinoma, forming a positive feedback loop with the arginine methyltransferase PRMT5." (PMID 38892284, 2024). "Conversely, in hepatocellular carcinoma, SMYD4 functions as an oncogene." (PMID 39482529, 2024).
breast tumour (1 paper, 2022). "Subsequently, it has been demonstrated that re-expression of Smyd4 (in breast tumour cells in which its expression had previously been suppressed) inhibited breast tumor cell and anchorage-independent growth." (PMID 36520265, 2022).
colon adenocarcinoma (1 paper, 2024). "In this analysis, colon and rectal tumors were evaluated separately, and it was observed that SMYD4 expression in colon adenocarcinoma was significantly lower in stage 2, 3, and 4 tumors (p = 1.04 × 10−3, 5.55 × 10−3, and 1.21 × 10−2, respectively) when compared to normal samples." (PMID 38892284, 2024).
congenital heart defects (1 paper, 2018). "More importantly, two rare genetic variants of SMYD4 were enriched in a 208-patient cohort with congenital heart defects." (PMID 30110327, 2018). "Importantly, we identified two rare SMYD4 genetic variants in a 208-patient cohort with congenital heart defects." (PMID 30110327, 2018).
endometrial carcinoma (1 paper, 2024). A malignant tumor arising from the epithelium that lines the cavity of the uterine body. "In endometrial carcinoma, the mutation frequencies were 3.3% for SMYD1, 2.1% for SMYD2, 2.1% for SMYD3, 2.1% for SMYD4, and 2.4% for SMYD5." (PMID 38892284, 2024).
leukemia (1 paper, 2024). A malignant (clonal) hematologic disorder, involving hematopoietic stem cells and characterized by the presence of primitive or atypical myeloid or lymphoid cells in the bone marrow and the blood. "This trend may be due to the fact that SMYD4 is located on 17p13.3, a region known to undergo heterozygous loss in various solid tumors and leukemias." (PMID 38892284, 2024).
lung adenocarcinoma (1 paper, 2024). A carcinoma that arises from the lung and is characterized by the presence of malignant glandular epithelial cells. "For patients with lung adenocarcinoma, a decrease in SMYD4 expression also resulted in a lower overall survival rate." (PMID 38892284, 2024).
melanoma (1 paper, 2025). A malignant, usually aggressive tumor composed of atypical, neoplastic melanocytes.
rectal adenocarcinoma (1 paper, 2024). "In rectal adenocarcinoma, significantly low expression of SMYD4 was only observed in stage 2 tumor samples (p = 1.86 × 10−2) when compared to normal sample." (PMID 38892284, 2024).
stomach adenocarcinoma (1 paper, 2024). "Moreover, SMYD4 showed low expression in tumor samples compared to normal samples, except for stomach adenocarcinoma." (PMID 38892284, 2024). "Interestingly, in the examined data from stomach adenocarcinoma, specifically those from stage 2, 3, and 4 tumors, SMYD4 exhibited higher expression levels compared to normal samples in most patients." (PMID 38892284, 2024).
uterine carcinosarcoma (1 paper, 2024). A usually aggressive malignant neoplasm arising from the uterine corpus and less often the cervix. "Moreover, in uterine carcinosarcoma, the mutation frequencies were 5.1% for SMYD1 and 2.5% for SMYD4." (PMID 38892284, 2024).
tumor (15 papers, 2015 to 2024). "High expression of SMYD4 has been implicated in the signaling pathways of cancer stem cells (CSCs), contributing to tumor cell transformation." (PMID 38892284, 2024). "SMYD4 exhibited a uniform alteration pattern, marked by a high incidence of heterozygous loss across all examined tumor types." (PMID 38892284, 2024). "Further research into the mechanisms underlying SMYD4’s tumor-suppressive functions is warranted to fully elucidate its clinical potential." (PMID 38892284, 2024). "Therefore, a loss in SMYD4 function might lead to a corresponding loss of function in other tumor suppressors." (PMID 38892284, 2024). "As the role of SMYD4 in cancer becomes more evident, further research is needed to better comprehend its mechanism of action in these tumor types." (PMID 38892284, 2024). "Collectively, these findings substantiate the role of SMYD4 as a potential tumor suppressor in various malignancies, reinforcing its importance in cancer biology and patient prognosis." (PMID 39335515, 2024). "To assess the expression of SMYD4 in normal samples and tumor samples at different disease stages, we profiled its mRNA expression using the UALCAN database." (PMID 38892284, 2024). "In BRCA, SMYD4 expression was also significantly lower in all tumor stages in comparison with normal samples (p < 1 × 10−12, p = 1.11 × 10−16, p < 1 × 10−12, and p = 1.96 × 10−12 for stages 1, 2, 3, and 4, respectively)." (PMID 38892284, 2024). "A correlation analysis was conducted to ascertain the relationship between SMYD4 copy number alterations (CNAs) and mRNA expression across various tumor types." (PMID 38892284, 2024). "In this study, we conducted an integrative multi-platform analysis using publicly available databases to investigate the prevalent molecular alterations in the genes of the SMYD family, specifically in SMYD4, across eight of the most common tumor types." (PMID 38892284, 2024). "Among other SMYD family genes, SMYD4 was the only one with such a consistent downregulation pattern across the different tumor types." (PMID 38892284, 2024). "Re-expression of SMYD4 has been shown to significantly reduce the expression of Pdgfr-alpha in tumor cells." (PMID 36520265, 2022). "The functional GRB2 protein acts as a negative regulator of the RAS pathway by inhibiting EGFRs, and SMYD4 is involved in inhibition of gene expression and has been suggested as a tumor suppressor gene." (PMID 32885540, 2020). "The results showed that the upregulation of SMYD4 enhanced Nanog expression at both the mRNA and protein levels in tumor cells." (PMID 32154082, 2020). "Hsa_circ_0004018 is transcribed from SMYD4, which is a potential tumor suppressor and plays critical roles in carcinogenesis, the development of heart and skeletal muscle, and hematopoiesis." (PMID 28938566, 2017). "We also demonstrated that SMYD4 consistently displayed a pattern of downregulation across a variety of tumor types, implying that its role as a tumor suppressor might be a universal characteristic in diverse oncological contexts." (PMID 38892284, 2024). "Notably, compared with normal tissue, tumor samples presented markedly lower expression levels of SMYD4, with the exception of GAC, whose expression levels were elevated." (PMID 39335515, 2024). "SMYD4 demonstrated its role as a tumor suppressor in the majority of tumors evaluated." (PMID 38892284, 2024). "In conclusion, our study highlights SMYD4 as a tumor suppressor gene across various solid tumors." (PMID 38892284, 2024). "In addition, recent reports have shown that miR-1307-3p promotes the tumor response by inhibiting SMYD4 expression." (PMID 38036730, 2023). "Only in BC, SMYD4 exerts anti-tumor effects through local inhibition of PDGFR-A." (PMID 34335697, 2021). "SMYD4 has been reported as a potential tumor suppressor and was involved in carcinogenesis, which prompted that, as a transcript of SMYD4, hsa_circ_0004018 might be involved in the development of HCC." (PMID 30191143, 2018).
tumor (continued). "Disruption of one SMYD4 allele in nontumorigenic mouse mammary epithelial cells results in tumorigenesis that is reversible with SMYD4 re-expression, suggesting that SMYD4 may be a potential tumor suppressor." (PMID 25825497, 2015). "Thus, if the function of SMYD4 observed in zebrafish is conserved and mirrors its role in humans, SMYD4 could potentially activate tumor suppressors through H3K4me3." (PMID 38892284, 2024). "Several PKMTs, including MLL3, PRDM2/RIZ, PRDM5, SMYD4, SUV4-20H2, and EEF1AKMT3, have been reported to exhibit tumor suppressor activities." (PMID 38036730, 2023). "Another microarray analysis revealed that a downregulated circRNA transcribed from SMYD4 and named hsa_circ_0004018, was correlated with serum AFP level, tumor diameters, differentiation, BCLC stage and TNM stage." (PMID 30191143, 2018). "With the exception of SMYD4, which exhibited a consistent downregulated pattern, all the other members of the SMYD family showed a distinct pattern of expression depending on the tumor." (PMID 38892284, 2024). "However, miR-1307 is involved in tumor development by influencing target genes, such as Forkhead box O3a (FOXO3A), SET And MYND Domain Containing 4 (SMYD4) and Disabled homolog 2-interacting protein (DAB2IP), to further promote cancer invasion." (PMID 37889117, 2023). "SMYD4 binds to the unmethylated Nanog promoter to activate Nanog expression in Nanog‐negative tumor cells." (PMID 32154082, 2020). "Importantly, a comparative analysis of SMYD4 expression between samples from normal tissues and samples from tumors at different stages revealed that SMYD4 expression is significantly decreased in cancer samples, regardless of the tumor stage." (PMID 38892284, 2024). "However, the molecular mechanism regarding the tumor-suppressive effect of SMYD4 in those tumors is not fully understood." (PMID 38036730, 2023).
cancer (10 papers, 2013 to 2026). A tumor composed of atypical neoplastic, often pleomorphic cells that invade other tissues. "The consistent downregulation of SMYD4, coupled with its association with cancer progression, underscores its potential usefulness as a biomarker." (PMID 38892284, 2024). "However, further research is needed to fully elucidate the molecular mechanisms underlying the dual role of SMYD4 in cancer progression." (PMID 39482529, 2024). "Although SMYD4 and SMYD5 have recently been associated with cancer, few studies have investigated these associations." (PMID 39482529, 2024). "The CNA containing the SET and MYND domain-containing protein 4 (SMYD4) gene on 17p13.3 was also reported previously in this cancer." (PMID 29083376, 2016). "To date, very few studies have examined the role of SMYD4 in cancer." (PMID 38892284, 2024). "However, a comprehensive understanding of the molecular alterations in SMYD4 within the context of a specific cancer remains largely unexplored." (PMID 38892284, 2024). "This suggests that SMYD4 expression could be explored as a valuable biomarker for predicting a more severe prognosis in this cancer type." (PMID 38892284, 2024). "The role of SMYD4 appears to be context dependent and can vary across different cancer types." (PMID 39482529, 2024). "One possible explanation for this intriguing alteration in SMYD4 expression in STAD may be that higher SMYD4 potentiates the expression of the transcription factor Nanog in cancer stem cells." (PMID 38892284, 2024). "The number of studies on SMYD4 and SMYD5 in the field of cancer has increased, although relatively few reports have compared SMYD4 and SMYD5 to SMYD2 and SMYD3." (PMID 39482529, 2024). "SMYD4 and SMYD5 are involved in cellular processes that are relevant to cancer development and progression, including gene regulation and cell signaling." (PMID 39482529, 2024). "To date, there are relatively few studies on the function of SMYD4 and SMYD5 in cancer, which necessitate further research." (PMID 36816359, 2023).
digestive system tumors (1 paper, 2021). "However, the role of SMYD4 in malignant digestive system tumors requires further investigation." (PMID 34335697, 2021).
infection (1 paper, 2019). The state of being infected such as from the introduction of a foreign agent such as serum, vaccine, antigenic substance or organism. "HDAC5, KDM2B, EZH1, PRDM2, SETMAR, SMYD4 and USP12 were differentially expressed at all time points post-infection (excluding 2 hpi)." (PMID 30728374, 2019).
SMYD4 also shares sentences with these, for which no sentence is quoted: glioblastoma (1 paper); lentivirus infection (1); male infertility (1); neuropathy (1); rectal tumors (1).